PCAT4 (prostate cancer associated transcript 4)
Synonyms: GDEP; PCAN1; PCA4
Gene: Long non-coding RNA gene on chromosome 4 (79,827,323 to 79,878,424, forward strand). Ensembl gene ENSG00000251321.
Diseases named in the same sentence as PCAT4 in open-access papers:
PCAT4 is named in the same sentence as 6 diseases in open-access papers, as found by Europe PMC text mining. Sharing a sentence is not in itself a finding about the gene and the disease. The quoted sentences say what the papers report.
prostate carcinoma (2 papers, 2008 to 2023). A carcinoma that arises from epithelial cells of the prostate gland. "The upregulated gene set included oncogenes such as PIK3CB, FGFRL1, and NCOA2; prostate cancer-related genes such as SPON2, PCAT4, and SCHLAP1; and cell cycle genes such as MKI67, MCM4, KIF4A, CENPF, and FLNB." (PMID 38067373, 2023).
PCAT4 also shares sentences with these, for which no sentence is quoted: tumor (3 papers); breast carcinoma (1); cancer (1); prostate tumor (1); rhinitis (1).